CAMKK2 (calcium/calmodulin dependent protein kinase kinase 2)
Diseases named in the same sentence as CAMKK2 in open-access papers (continued):
Sharing a sentence is not in itself a finding about the gene and the disease.
tumor (continued). "Comparable levels of phospho-CaMKI were detected in RM-BMDM and TCM-BMDM, from both WT and Camkk2−/− mice, indicating that tumor-derived factors are not increasing all aspects of CaMKK2 signaling in BMDM." (PMID 31164648, 2019). "This intervention was accompanied by a dramatic increase in tumor growth in the Camkk2−/− background, but was without effect in WT mice." (PMID 31164648, 2019). "STO-609 was without effect in CD8+ T cell depleted Camkk2−/− mice, suggesting that its actions in primary tumor growth are likely limited to immune cells." (PMID 31164648, 2019). "Overexpression of CaMKK2 did not correlate with tumor grade, although a significant positive correlation between the expression of CaMKK2 in tumors and stromal cells was identified." (PMID 31164648, 2019). "Additionally, immunostaining of CaMKK2 and TIPRL in a similar tumor region stained strongly." (PMID 39076120, 2024). "Camkk2 status did not influence prostate/primary tumor weight in obese TRAMP mice." (PMID 35741020, 2022). "These may represent an additional non-hematopoietic CaMKK2-expressing cell with pro-tumor roles in GBM." (PMID 36309495, 2022). "However, the percentage of CD8+ GranzymeB+ PD1- TIL, a phenotype associated with non-exhausted effector T cells, was increased in E.G7-OVA tumor removed from Camkk2-/- compared to WT mice." (PMID 34712241, 2021). "Tumor growth was suppressed in Camkk2-/- mice that received no treatment or isotype IgG control, while the treatment with anti-CD8 depleting antibody reversed the protective effects of Camkk2 deletion, enabling the growth of E.G7-OVA." (PMID 34712241, 2021). "Interestingly, CAMKK2 is a top feature found only in the P0119-T1 CAF and not the tumor models." (PMID 39221276, 2024).
infection (12 papers, 2010 to 2025). The state of being infected such as from the introduction of a foreign agent such as serum, vaccine, antigenic substance or organism. "Naïve Huh7 cells inoculated with cell- culture-produced infectious HEV particles did not affect the expression of AMPKα or its upstream regulatory kinase genes CAMKK1, CAMKK2 and STK11 at the transcriptional level at 24 h post-infection." (PMID 40074929, 2025). "Elevated calcium influx stimulated the activation of CaMCCK2 (calcium/calmodulin-dependent protein kinase kinase 2) and its downstream effector AMPK, thus inducing autophagy in early infection." (PMID 36321903, 2022).
metabolic disease (7 papers, 2019 to 2025). A congenital disorder (due to inherited enzyme abnormality) or acquired (due to failure of a metabolically important organ) disorder resulting from an abnormal metabolic process. "The calcium (Ca2+)/calmodulin (CAM)-activated kinase kinase 2 (CAMKK2)-signaling regulates several physiological processes, for example, glucose metabolism and energy homeostasis, underlying the pathogenesis of metabolic diseases." (PMID 34563205, 2021).
neurological disorders (6 papers, 2019 to 2024). "In this context, it is important to note that CAMKK2 has emerged as a target for several neurological disorders." (PMID 39669708, 2024). "As such, we not only explored the possible role of miR-21-3p in the CI/R domain for the first time and provided support for its impact on neurological diseases but also provided further evidence for the important role of CAMKK2/AMPK in CI/R therapy." (PMID 37132110, 2023). "The deregulation of CAMKK2 has implications in oncological, metabolic and neurological diseases." (PMID 31941153, 2020).
neurodegenerative disease (5 papers, 2020 to 2026). A disorder of the central nervous system characterized by gradual and progressive loss of neural tissue and neurologic function. "Further studies are needed to explore the pathways linking CAMKK2 and iron dysregulation in AD and other neurodegenerative diseases." (PMID 39669708, 2024). "Overall findings in this study and our previous studies highlights CAMKK2 as a potential therapeutic target for modulating iron homeostasis in neurodegenerative diseases." (PMID 39669708, 2024). "This consistency across two different neurodegenerative diseases highlights CAMKK2’s potential role in broader neurodegenerative processes beyond AD." (PMID 39669708, 2024). "Therefore, altered Ca2+ in neurodegenerative diseases may affect CAMKK2 function leading to increased TF turnover and iron deposition in the brain which may lead to iron-induced toxicity and neuronal damage." (PMID 32460794, 2020). "Furthermore, they suggest that CaMKK2 has roles in maintaining the DAM phenotype, which likely has implications in other neurodegenerative diseases, like Alzheimer’s." (PMID 36309495, 2022).
myopathies (2 papers, 2016 to 2022). "As CaMKK2 levels are up-regulated in DMD patients, CaMKK2 inhibition maybe serve as a potential target to maintain skeletal muscle functions and provide a therapeutic strategy to treat patients with muscle injury or severe myopathies." (PMID 27783047, 2016). "Lastly, we show that overexpressing CaMKK2 in the muscle of mice via electroporation impaired the muscle regeneration during freeze-induced injury, indicating that CaMKK2 could serve as a potential target to treat patients with muscle injury or myopathies." (PMID 27783047, 2016).
adenocarcinoma (1 paper, 2022). A common cancer characterized by the presence of malignant glandular cells. "Importantly, Camkk2 ablation blocked progression to primary adenocarcinoma." (PMID 35741020, 2022). "Here, we demonstrate that germline ablation of Camkk2 slows, but does not stop, primary prostate tumorigenesis in the TRansgenic Adenocarcinoma Mouse Prostate (TRAMP) genetic mouse model." (PMID 35741020, 2022).
blood cancers (1 paper, 2017). "Furthermore, CaMKK2 inhibition may prevent blood cancers associated with the radiation treatment." (PMID 28981105, 2017). "Camkk2 null mice do not develop a progressive exhaustion of the hematopoietic compartment or blood cancer with age (LR personal communication)." (PMID 28981105, 2017).
heart disease (1 paper, 2024). "Significantly, adenovirus-mediated overexpression of Ckip-1 3'UTR alleviated SD-induced cardiac dysfunction and remodeling by activating CaMKK2/AMPK/cTNI pathway, which proposed the therapeutic potential of Ckip-1 3'UTR in treating SD-induced heart disease." (PMID 38871861, 2024).
CAMKK2 also shares sentences with these, for which no sentence is quoted: neuroblastoma (6 papers); HCMV infection (5); Stroke (5); colorectal cancer (4); atherosclerosis (3); Bladder (3); leukemia (3); Type 2 diabetes (3); anxiety disorder (2); breast tumor (2); colon cancer (2); cyst (2); dementia (2); hepatic disease (2); ischemia (2); kidney diseases (2); prostate (2); acute kidney injury (1); acute liver failure (1); astrocytoma (1); Atrophy (1); autosomal dominant polycystic kidney disease (1); bacterial infection (1); Benign Prostate Hyperplasia (1); bladder cancer (1); brain edema (1); cardiomyopathy (1); dystrophinopathy (1); endometriosis (1); ependymoma (1).
A further 29 diseases each share a sentence with CAMKK2 in 1 paper.